FNBP4 (formin binding protein 4)
Synonyms: FBP30; KIAA1014
Tractability: PROTAC: UniProt records ubiquitination sites on it; ubiquitination databases record sites on it; its protein half-life has been measured.
Gene: Protein-coding gene on chromosome 11 (47,716,494 to 47,767,443, reverse strand). Ensembl gene ENSG00000109920.
Subcellular location (Human Protein Atlas): Nucleoplasm
Gene Ontology:
Molecular function: protein binding
Cellular component: nucleoplasm
Genetic constraint (gnomAD): Loss-of-function variants: 24 observed, 95.97 expected, observed/expected ratio (o/e) 0.25, 90% interval 0.18 to 0.35. The upper end of that interval is the gene's LOEUF score, 0.35, which puts it in group 1 of 6, group 1 being the genes least tolerant of losing a copy. Missense variants: 969 observed, 1,053.6 expected, observed/expected ratio (o/e) 0.92, 90% interval 0.87 to 0.97. Synonymous variants: 393 observed, 366.69 expected, observed/expected ratio (o/e) 1.07, 90% interval 0.99 to 1.16.
Homologues: Orthologues: chimpanzee FNBP4 (99% identical), macaque FNBP4 (98% identical), dog FNBP4 (93% identical), pig FNBP4 (92% identical), rabbit FNBP4 (91% identical), rat Fnbp4 (87% identical), mouse Fnbp4 (87% identical), guinea pig FNBP4 (84% identical), tropical clawed frog fnbp4 (53% identical), zebrafish fnbp4 (46% identical), Drosophila melanogaster Frl (14% identical), Caenorhabditis elegans daam-1 (13% identical), and 3 more. Paralogues in human: FMNL2 (14% identical), DIAPH1 (14% identical), FMNL1 (13% identical), FMNL3 (13% identical), DIAPH3 (12% identical), FHOD3 (12% identical), FMN2 (12% identical), DAAM1 (12% identical), DIAPH2 (12% identical), DAAM2 (12% identical), INF2 (11% identical), GRID2IP (10% identical), and 6 more.
Diseases named in the same sentence as FNBP4 in open-access papers:
FNBP4 is named in the same sentence as 7 diseases in open-access papers, as found by Europe PMC text mining. Sharing a sentence is not in itself a finding about the gene and the disease. The quoted sentences say what the papers report.
Alzheimer disease (1 paper, 2021). A progressive, neurodegenerative disease characterized by loss of function and death of nerve cells in several areas of the brain leading to loss of cognitive function such as memory and language. "STX3, one of the novel TWAS significant genes was dropped after conditional analysis along with three of the genes in Alzheimer’s disease risk loci: FNBP4, MYBPC3 and MS4A6A." (PMID 33959712, 2021).
hepatocellular carcinoma (1 paper, 2024). A malignant tumor that arises from hepatocytes. "To date, FNBP4 expression has been correlated with poor OS in hepatocellular carcinoma." (PMID 39201394, 2024).
liver cancer (1 paper, 2024). An epithelial or non-epithelial malignant neoplasm that arises from the liver. "After data analysis, it was found that the expression of FNBP4 in liver cancer increased significantly, and a high expression of FNBP4 was negatively correlated with the patient’s OS." (PMID 38200525, 2024).
cancer (2 papers, 2024 to 2025). A tumor composed of atypical neoplastic, often pleomorphic cells that invade other tissues. "Notably, FNBP4 has been identified as a prognostic marker for cancer." (PMID 40316024, 2025). "The remaining eight target genes (CFL1, FNBP4, NDUFB3, OCIAD2, PLIN3, POU2AF1, RAC1, TMEM141) presented a combined influence in five or fewer cancer types." (PMID 39201394, 2024). "Further studies are necessary to establish whether FNBP4 physiologically regulates FMN1 in the nucleus and promotes cancer progression by modulating nuclear actin dynamics." (PMID 40316024, 2025).
tumor (2 papers, 2021 to 2025). "FCHSD1 may functionally cooperate with interacting genes (e.g., SBK1, ITSN2, and FNBP4) to collectively drive tumor malignancy, thus warranting further mechanistic investigations to elucidate these molecular interactions." (PMID 40535123, 2025). "FCHSD1 may functionally interact with SBK1, ITSN2, and FNBP4 to collectively regulate malignant tumor progression." (PMID 40535123, 2025).
FNBP4 also shares sentences with these, for which no sentence is quoted: breast carcinoma (2 papers); atherosclerosis (1).